CXCR2 (C-X-C motif chemokine receptor 2)
Diseases named in the same sentence as CXCR2 in open-access papers (continued):
Sharing a sentence is not in itself a finding about the gene and the disease.
ovarian carcinoma (continued). "A primary finding of this study is that CXCR2-driven cancer progression involves upregulation of its own ligands such as CXCL1 and CXCL2 by potentiating NF-κB activation via EGFR-transactivated Akt signaling followed by accelerated ovarian cancer cell proliferation, migration and invasion." (PMID 24376747, 2013). "However, when treated with the Reparixin (inhibitor of IL‐8 receptors CXCR1 and CXCR2), the migration of ovarian cancer cells decreased compared with the control group no matter whether treated or not treated with the IL‐8." (PMID 31793192, 2020). "Probably, CXCR2 positive ovarian cancer cells could potentiate the NF-κB mediated CCL20 in proinflammatory tumor microenvironment via interaction between ovarian cancer and cancer-associated stromal cells compared to CXCR2 negative cells." (PMID 27723802, 2016). "CXCR1 and CXCR2 were downregulated in ovarian cancer tissues, while CXCR5 and CXCR6 were not significantly different between ovarian cancer and normal tissues." (PMID 33829065, 2021). "As described in detail previously, CXCR2 positive ovarian cancer cells exert highly activated EGFR-downstream signaling such as Akt and Erk and NF-κB, compared to CXCR2 negative cells." (PMID 27723802, 2016). "Based on the negative effects of CXCR2 on romidepsin-induced p21, IC50 of romidepsin and clonogenic colony formation, CXCR2 could be resistant to romidepsin treatment in ovarian cancer." (PMID 29515768, 2018). "Furthermore, as described in detail previously, CXCR2 positive ovarian cancer cells enhanced more the promoter activity and mRNA levels of CXCL1 and 2 by NF-κB potentiation through EGFR-activated Akt compared to CXCR2 negative cells." (PMID 27723802, 2016).
asthma (50 papers, 2009 to 2025). "CXCL5 regulates neutrophil trafficking to the lung via CXCR2 and has been implicated in asthma and multiple cancers." (PMID 38355791, 2024). "In this sense, CXCR2 is expressed on endothelial cells in the lungs and may be linked to the augmented angiogenesis in the airway mucosa, a characteristic of both human asthma and COPD." (PMID 33123138, 2020). "Because the recruitment of neutrophils to sites of inflammation involves CXCR2, a high-affinity receptor for IL-8, CXCR2 antagonists have been developed and tested as an add-on to standard therapy in patients with persistent uncontrolled asthma." (PMID 41145900, 2025). "In respiratory diseases like chronic obstructive pulmonary disease (COPD) and asthma, CXCR2 is crucial for neutrophil chemotaxis to the airways, exacerbating inflammation and tissue damage." (PMID 39062109, 2024). "The other essential point is the implication of CXCL1-CXCR2 signaling-mediated neutrophil suppression in allergic airway inflammation that should be further investigated during the development of CXCR1/CXCR2 inhibition therapy for asthma treatment." (PMID 39767651, 2024). "Cxcl2 can also recruit Cxcr2+ endothelial progenitor cells into the lungs of allergen-sensitized mice and CXCL2-CXCR2 in asthma patients." (PMID 39768150, 2024). "And these chemokines follow the same expression pattern as their shared receptor CXCR2, in the lung tissue of asthma mice." (PMID 38459541, 2024). "AZD5069, a selective and reversible CXCR2 antagonist, has been evaluated in respiratory conditions such as bronchiectasis, asthma, and COPD in differing doses." (PMID 35158784, 2022). "For example, the antagonism of the chemokine receptor CXCR2 was able to reduce neutrophil recruitment and improved tissue damage in asthma, in LPS-induced acute inflammation, and in bleomycin-induced lung fibrosis." (PMID 35682923, 2022). "Inhibition of Cxcl3 in a mouse model of RV-induced exacerbation of asthma decreased the accumulation of Cxcr2+ neutrophils." (PMID 34557202, 2021). "Several clinical trials have provided evidence implicating the CXCL1/CXCR2 axis as a therapeutic target for asthma, bronchiectasis, and cancer, with promising effects in chronic obstructive pulmonary disorder (COPD)." (PMID 33087182, 2020). "Navarixin, a selective CXCR1 and CXCR2 antagonist, was tested in patients with allergen-induced asthma and severe neutrophilic asthma." (PMID 33123138, 2020). "Small molecule CXCR2 antagonists have been extensively tested in clinical trials for asthma, chronic obstructive pulmonary disease (COPD) and influenza." (PMID 32581816, 2020). "Inhibition of CXCR1 and CXCR2 by Ladarixin prevented airway hyperreactivity, the main asthma manifestation in those animals." (PMID 33123138, 2020). "Experiments using various animal models of asthma have suggested the relevance of CXCR2 and its ligands in the pathogenesis of the disease." (PMID 33123138, 2020). "A six-gene signature (CLC, CPA3, DNASE1L3, IL1B, ALPL, and CXCR2) can differentiate asthma patients from controls, discriminate inflammatory phenotypes of asthma and predict the ICS response, but this method is not currently available." (PMID 30598830, 2018). "Related studies have been carried out on patients with asthma who were treated with CXCR2 antagonists to inhibit neutrophil infiltration." (PMID 29359169, 2017). "IL33-induced CXCR2 up-regulation is required for neutrophil activation in a mouse model of asthma mediated by immunoglobulin E." (PMID 28742815, 2017). "A recent study demonstrated that CXCR2 inhibitor reduced sputum neutrophilia and asthma exacerbations, and improved Asthma Control Questionnaire (ACQ) score in patients with severe asthma." (PMID 26011707, 2015). "Pharmacologic CXCR2 inhibition in healthy humans, using ozone- or LPS-induced inflammation models, or in patients with severe asthma or cystic fibrosis showed that CXCR2 inhibition is safe and decreases neutrophilic inflammation in the airways." (PMID 25764063, 2015).
asthma (continued). "SB 265610, a competitive antagonist of chemokine (CXC-motif) receptor 2 (CXCR2), attenuated the increased sprout outgrowth induced by CM of asthma patient-derived BSMC." (PMID 24339939, 2013). "Viral and bacterial lung infections contribute significantly to the frequency of asthma exacerbations and studies in animals have shown an important role for CXCR2 in this response." (PMID 22936934, 2012). "CXCR2 antagonism has demonstrated promising results in several chronic inflammatory diseases in which neutrophils play a key role, such as cystic fibrosis, asthma, and chronic obstructive pulmonary disease." (PMID 40598560, 2025). "The CTD database was used to predict the underlying therapeutic agents associated with asthma severity, and we noted that Reparixin may have great significance for precision treatment of asthma, targeting MMP9, CXCR1 and CXCR2." (PMID 38351296, 2024). "Cxcl3 may be critical for perpetuating rhinovirus-induced asthma exacerbation through the recruitment of Cxcr2+ neutrophils and by promoting type 2 inflammation." (PMID 39768150, 2024). "However, the clinical effectiveness of CXCR2 antagonists in the treatment of asthma is currently uncertain." (PMID 38283037, 2023). "For example, the CXCR2 antagonists’ effect is documented in a group of patients with asthma." (PMID 34947883, 2021). "As in asthma, non-Th2 inflammation targets include CXCR2 and CCR3." (PMID 33297418, 2020). "Moreover, a recent clinical trial in patients with severe asthma and sputum neutrophils has found that the CXCR2 antagonist SCH527123 is safe to use in clinical settings." (PMID 30871004, 2019). "This could lead to a feed-forward process of smoke-triggered CXCR2-dependent neutrophil accumulation, thereby maintaining the chronicity of NETopathic inflammation in the airways of the asthma smoking phenotype." (PMID 30804927, 2019). "Notably, ALPL, along with IL8RB/CXCR2, was identified as an expression biomarker of asthma inflammatory subtypes." (PMID 27417541, 2016). "Furthermore, blockade of the murine CXCL8 receptors CXCR1 and CXCR2 reduced neutrophilic airway inflammation in mouse models of various pulmonary conditions including asthma." (PMID 25713319, 2015). "If the results of our study are confirmed in mechanistic and large-scale BAL fluid studies, inhibition of neutrophil recruitment by CXCR2 inhibitors and others agents should be explored as alternate therapeutic strategies in uncontrolled asthma with elevated neutrophils." (PMID 26011707, 2015). "Counteracting the CXCR2-mediated neovascularization by pharmaceutical compounds may represent a novel strategy to reduce airway remodelling in asthma." (PMID 24339939, 2013). "Increased production of the CXCR2 ligands ENA-78, GRO-α and IL-8 was confirmed by ELISA and functionality of CXCR2 ligands in mediating proangiogenic effects of BSMC from asthma patients was demonstrated by reduction of EC sprout outgrowth in the presence of the specific CXCR2 antagonist SB 265610." (PMID 24339939, 2013). "Recently, AZD5069 has been shown to diminish CXCR2-mediated neutrophil infiltrates in spontaneous sputum from bronchiectasis patients (69% inhibition), as well as pronounced reduction in induced sputum and bronchial biopsies from patients with more severe asthma (90% inhibition)." (PMID 30804927, 2019). "In the present study, the in vivo pharmacology of a potent CXCR2 antagonist AZD8309 was evaluated in healthy human subjects using inhalation of LPS, a method which closely replicates key components of the inflammatory response associated with COPD, severe asthma and CF." (PMID 24341382, 2013). "In asthma, MIF induces CCl2, CXCR2, and CXCR4 expression through the ERK / MAPK / P38 / Rho A GTPase pathway." (PMID 37422662, 2023). "Nevertheless, the relationship between CXCR1, CXCR2, TLR2 and asthma severity was stable, and combined hub genes were able to discriminate severe asthmatics from mild-moderate asthmatics in ROC analysis." (PMID 33602227, 2021).
asthma (continued). "The correlation analysis results showed that CXCR1 (P = 0.02), CXCR2 (P = 0.02), and TLR2 (P = 0.01) were significantly related to asthma severity in GSE43696." (PMID 33602227, 2021). "A third CXCR2 antagonist, SCH527123 (Merck), inhibited lung neutrophil influx in asthma patients, and decreased neutrophilia in healthy humans exposed to toxic levels of ozone." (PMID 32581816, 2020). "In this direction, Danarixin and Navarixin inhibited both CXCR1 and CXCR2 functions in most of the clinical trials of COPD, asthma and influenza infection." (PMID 33123138, 2020). "In fact, phase 2 interventional clinical trials on asthma, influenza infection or COPD have been already performed using the CXCR1 and CXCR2 inhibitors." (PMID 33123138, 2020). "AZD5069 (AstraZeneca) is a selective CXCR2 antagonist that has been tested for safety and efficacy in pre-clinical and clinical studies of COPD and asthma." (PMID 32581816, 2020). "Targeting of CXCL1 or its receptor CXCR2 with blocking antibodies was recently shown to reduce AHR and goblet cell metaplasia in a murine asthma model." (PMID 27621809, 2016). "Hence, CXCR2 could be an interesting target for therapy in RV‐induced asthma exacerbations." (PMID 24673807, 2014). "Several studies have identified an important role for CXCR2 in acute lung injury (ALI), asthma, COPD, and cystic fibrosis." (PMID 22936934, 2012). "In this context, it isinteresting the recently suggested correlation between obesity and asthma.Strikingly, exacerbation of asthma has been also correlated with increasedexpression of both CXCL5 and its receptor CXCR2." (PMID 20157549, 2009). "Notably, Reperixin displays the ability to target CXCR1, CXCR2, and MMP9, suggesting its potential therapeutic value for managing deteriorating asthma." (PMID 38351296, 2024). "CXCR2 antagonist AZD5069 is being studied for reducing the number of neutrophils in the sputum of severe asthma patients, however there is no reduction in the frequency of severe exacerbations." (PMID 38283037, 2023). "Furthermore, hub genes, such as CXCR1, CXCR2, and TLR2, were identified as biomarkers of asthma severity through either the neutrophil inflammation pathway or Th17 immune pathway." (PMID 33602227, 2021). "Both the six gene signature (6GS: CPA3, DNASE1L3, CLC, IL1B, ALPL, and CXCR2) and T‐helper 2 signature (TH2S: CLCA1, SERPINB2, and POSTN) are proposed as biomarkers in the identification of inflammatory phenotypes of asthma in induced sputum and epithelial brushings, respectively." (PMID 31903716, 2020). "Among those showing positive effects, the CXCR2 inhibitor MK-7123 (also known as SCH527123 or navarixin, already described in asthma) could reduce the chemotaxis of neutrophils." (PMID 33297418, 2020). "There is a growing body of evidence indicating that CXCR1 and CXCR2 may have a role in the pathogenesis of certain pulmonary diseases, including COPD, lung fibrosis and asthma." (PMID 33123138, 2020). "In this context, the exclusion of patients who were current smokers or ex-smokers (smoking history of ≥ 20 pack years) in this clinical study, meant that it was not possible to determine the therapeutic potential of CXCR2 antagonists in smokers with asthma." (PMID 30804927, 2019). "Despite the observed neutrophil infiltrate lowering effects in severe asthma, results from trials of orally-active CXCR2 antagonists have not shown any clinical benefits to date." (PMID 30804927, 2019). "Although potent CXCR2 antagonists have been reported, most of the antagonists under clinical trials were tested in non-cancerous diseases like asthma, airway inflammation, and coronary heart diseases." (PMID 31390756, 2019). "Treatment with another oral CXCR2 antagonist (MK-7123) was shown to attenuate sputum neutrophilia by 36% in patients with severe asthma (n = 34), yet had no clinical effect on asthma outcomes." (PMID 30804927, 2019).
asthma (continued). "A recent study demonstrated that CXCR2 inhibitor reduced the sputum neutrophilia and showed a trend towards exacerbation and improvement of Asthma Control Questionnaire (ACQ) score in patients with severe asthma." (PMID 29849682, 2017). "CXCR2 is a receptor for a number of chemokines such as the GRO family (CXCL1-3) and CXCL8, all of which are elevated in respiratory inflammatory diseases such as COPD, severe asthma, and acute respiratory distress syndrome." (PMID 28596972, 2017). "However, AZD5069, which is also an antagonist of CXCR2, failed to reduce asthma exacerbations or improve lung function compared with placebo." (PMID 33602227, 2021). "In this Review, we discuss the emerging role of NETs in the clinicopathobiology of COPD and severe asthma and provide an outlook on how novel NET-stabilizing therapies via CXCR2 blockade could be leveraged to disrupt NETopathic inflammation in disease-specific phenotypes." (PMID 30804927, 2019). "In this regard, novel small molecules targeting neutrophilic inflammation, such as chemokine (CXC) receptor 2 (CXCR2) antagonists have been analyzed in the noneosinophilic asthma context, showing how these antagonists reduce neutrophils, but do not improve clinical outcomes in studies to date." (PMID 29977241, 2018). "The promising profile of AZD5069, a CXCR2 inhibitor, in a chronic obstructive pulmonary disease (COPD) model was not replicated in asthma either, with only a decrease in neutrophil counts in patients' sputum but no improvement in overall clinical outcome." (PMID 36164329, 2022).
gastric cancer (46 papers, 2010 to 2025). A primary or metastatic malignant neoplasm involving the stomach. "CXCR2 has been implicated in the metastasis of various cancers, including esophageal cancer, laryngeal cancer, and gastric cancer." (PMID 31390756, 2019). "Earlier studies by our group have shown that SPARC, CLIC1, SLPI, CXCL1, CXCL8, and CXCR2 are highly expressed and associated with advanced stages and poor prognosis of gastric cancer." (PMID 22479608, 2012). "Finally, myelokathexis is not pathognomomic of WS, as it is observed in other situations such as in neutropenia linked to the glucose 6 phosphatase, catalytic subunit 3 (G6PC3), CXCR2 loss-of-function mutations or in gastric cancer." (PMID 23009155, 2012). "Inhibiting the CXCR2 pathway in gastric cancer cells suppresses the migration and metastasis of gastric cancer in vitro and in vivo." (PMID 41583453, 2025). "A study reported that the expression of CXCR4 and CXCR2 is positively correlated in gastric cancer and that a positive feedback loop is formed between P65/CXCR4 and STAT3/CXCR2, which induces EMT and promotes metastasis." (PMID 40722739, 2025). "Inhibiting CXCR2 pathway of gastric cancer cells can suppress migration and metastasis of gastric cancer in vitro and in vivo." (PMID 41583453, 2025). "PADI4 plays a role in gastric cancer by upregulating the expression of C-X-C motif chemokine receptor 2 (CXCR2), keratin 14 (KRT14), and tumor necrosis factor (TNF-α)." (PMID 37804426, 2023). "Consistently, our results showed a higher CXCL1 expression in gastric cancer patient samples, which was positively correlated with CXCR2 expression." (PMID 36614235, 2023). "The downregulation of PADI2 can lead to the low expression of CXCR2, thus inhibiting the proliferation and migration of gastric cancer cells and promoting apoptosis." (PMID 37020554, 2023). "Protein–protein interaction and co-expression analysis showed a strong association of CXCL1 with CXCR1, CXCR2, IL6, and IL1B in human gastric cancer tissue samples." (PMID 36614235, 2023). "CXCL5 derived from TAMs in gastric cancer promotes metastasis by activating the CXCR2/STAT3 feed-forward loop." (PMID 35853880, 2022). "CXCR2 ligands, produced by TAM, significantly promote proliferation and migration of gastric cancer cells through activating a CXCR2/STAT3 feed-forward loop." (PMID 34012923, 2021). "Conversely, the inhibition of CXCR2 pathway in gastric cancer cells suppressed migration and metastasis of gastric cancer both in vitro and in vivo." (PMID 34012923, 2021). "The correct reference is “Wang, Z.; Liu, H.; Shen, Z.; Wang, X.; Zhang, H.; Qin, J.; Xu, J.; Sun, Y.; Qin, X. The prognostic value of CXC-chemokine receptor 2 (CXCR2) in gastric cancer patients." (PMID 31146450, 2019). "CXCR2 has been recognized as a predictor for the prognosis of gastric cancer patients, and also as a promising therapeutic target." (PMID 30984000, 2019). "CXCL1 and CXCR2 are expressed in both gastric cancer cells and stromal cells including fibroblasts and macrophages in our study." (PMID 28575019, 2017). "The effect of gastric cancer cells on the expression of CXCR2 in BM-MCs was examined using diffuse-type gastric cancer cell lines in vitro." (PMID 28575019, 2017). "In contrast, our study reported the role of cancerous CXCL1 expression and CXCR2 expression of stromal fibroblasts in gastric cancer." (PMID 28575019, 2017). "Both CXCL1 expression in cancer cells and CXCR2 expression in stromal cells were independent prognostic factors for gastric cancer patients." (PMID 28575019, 2017). "The expressions of CXCL1 in cancer cells and CXCR2 in stromal cells are useful prognostic factors for gastric cancer patients." (PMID 28575019, 2017). "We currently reported that CXCL1 from gastric cancer cells stimulates CXCR2 signalling of BM-MCs which become myofibroblasts in tumor stroma using cell lines." (PMID 28575019, 2017).